HIF1A (hypoxia inducible factor 1 subunit alpha)
Diseases named in the same sentence as HIF1A in open-access papers (continued):
Sharing a sentence is not in itself a finding about the gene and the disease.
Telangiectasia (4 papers, 2015 to 2025). Telangiectasias refer to small dilated blood vessels located near the surface of the skin or mucous membranes, measuring between 0.5 and 1 millimeter in diameter. "Elevated IL-6 and HIF-1α further linked hypoxia to vascular alterations, with HIF-1α correlating with telangiectasia." (PMID 41373451, 2025). "HIF-1α levels were positively correlated with disease severity (r = 0.374, p = 0.017) and were higher in patients with telangiectasia (p = 0.016)." (PMID 41373451, 2025). "VEGF and HIF-1α are both crucial in the regulation of angiogenesis, erythropoiesis and iron metabolism, and therefore, the reduction of their expression may result in reduced redness and telangiectasia observed in rosacea." (PMID 39275081, 2024). "Another split-face pilot study by Domingo in patients with erythema and telangiectasia (n = 4) demonstrated that although symptoms did not improve, HIF-1α and VEGF expression were reduced compared to vehicular control." (PMID 26044054, 2015).
Thiamine deficiency (4 papers, 2017 to 2024). Thiamine deficiency is a condition that occurs due to not enough thiamine (vitamin B1). "Induction of thiamine deficiency in mouse primary astrocytes resulted in an ~3 fold increase in total HIF-1α expression as early as 24h of pyrithiamine (PT) treatment, which was maintained with minimal fluctuation in expression for up to 14 days." (PMID 29045486, 2017). "The HIF-1α target gene LDHA was induced by thiamine deficiency, and subsequently reduced following thiamine repletion, although the protein did not return to control levels." (PMID 29045486, 2017). "This would also partly explain why thiamine deficiency is associated with HIF1A stabilization." (PMID 30809153, 2019). "Thiamine deficiency leads to an accumulation of metabolic intermediates, such as pyruvate and lactate, which stabilize HIF-1α through inhibition of prolyl hydroxylases (PHDs), thereby inducing HIF-1α-mediated gene expression." (PMID 39575238, 2024).
uremia (4 papers, 2017 to 2024). A clinical syndrome associated with the retention of renal waste products or uremic toxins in the blood. "Additionally, several studies in CKD animal models suggest that HIF-1α is suppressed by factors including oxidative stress and uremia and underlies the pathogenesis of CKD18." (PMID 28106131, 2017). "NIH/3T3 cells exposed to uremia demonstrated higher HIF-1α activity consistent with the elevated lactate production." (PMID 33536542, 2021). "Our data show that adipocytes and macrophages exposed to uremia increase inflammatory cytokine secretion and activation of NFκB/HIF1α." (PMID 33536542, 2021). "3T3/NIH cells exposed to uremia had NFκB and HIF1α activation highlighting a role of both transcription factors in the inflammatory response of uremia." (PMID 33536542, 2021).
urothelial carcinoma (4 papers, 2023 to 2025). A malignant neoplasm derived from the transitional epithelium of the urinary tract (urinary bladder, ureter, urethra, or renal pelvis). "A recent Mint3-related study on urothelial carcinoma also indicated that the depletion of Mint3 downregulates the invasion, migration, and proliferation of cancer cells, accompanied by factors associated with suppressed HIF-1α activity, such as transcription of HIF-1α-targeted genes and glycolysis." (PMID 36831085, 2023). "PKM2 gene ablation in cancer cells led to reduced growth and apoptosis and in a H-ras-driven urothelial carcinoma model in mice, it was shown to control angiogenesis via regulation of hypoxia inducible factor 1 alpha (HIF1α) and VEGF expression." (PMID 37569686, 2023).
Wilms tumor (4 papers, 2011 to 2024). An embryonal neoplasm characterized by the presence of epithelial, mesenchymal, and blastema components. "In addition, induction of HOXA11-AS by hypoxia/inflammation upregulated of HIF-1α and C/EBPβ further to promote epithelial-mesenchymal transition ability of nephroblastoma." (PMID 38902760, 2024).
acute coronary syndrome (3 papers, 2020 to 2022). Signs and symptoms related to acute ischemia of the myocardium secondary to coronary artery disease. "The aim of our study was to investigate the influence of a two-week cardiac rehabilitation programme on HIF-1A, NfkB and NILCO-dependent leptin and VEGF A cross-talk in patients after acute coronary syndrome." (PMID 35821400, 2022). "This study aimed to investigate the influence of cardiac rehabilitation (CR) on HIF-1A, NfkB and NILCO dependent leptin and VEGF A cross-talk in patients after acute coronary syndrome (ACS)." (PMID 35821400, 2022). "When cells are hypoxic, HIF-1α enhances the transcription and expression of VEGF, thereby stimulating new angiogenesis, promoting AS and increasing plaque instability, promoting plaque rupture and inducing acute cardiovascular events, which may be the pathogenesis of acute coronary syndrome." (PMID 35069552, 2021).
adenomyosis (3 papers, 2022 to 2025). The growth of endometrial tissue inside the muscular wall of the uterine corpus. "Recent transcriptomic analyses in adenomyosis further support this concept by demonstrating enrichment of angiogenesis-related pathways—including HIF-1α/VEGF signaling—in eutopic and ectopic endometrium." (PMID 41464535, 2025). "Recent transcriptomic profiling supports this concept, showing that eutopic and ectopic endometrium in adenomyosis exhibits enrichment of angiogenesis-related pathways, including HIF-1α/VEGF signaling." (PMID 41464535, 2025). "As adenomyosis lesions progress and become more fibrotic and thus stiffer, the HIF‐1α and PGE2 signaling in these lesions also becomes progressively suppressed." (PMID 35386380, 2022). "As a result, there may be a subsequent suppression of PGE2 as well as HIF‐1α signaling in adenomyosis lesions and their neighboring EMI and endometrium, with ensuing impaired and disrupted endometrial repair and, ultimately, HMB." (PMID 35386380, 2022). "There is a close but inverse correlation between the extent of fibrosis and the immunostaining levels of HIF‐1α, COX‐2, EP2, and EP4 in adenomyosis lesions and EMI tissues, and also in eutopic endometrium." (PMID 35386380, 2022). "In addition, we found that the increased adenomyosis lesional fibrosis is accompanied by reduced HIF‐1α and PGE2 immunostaining and possibly signaling in lesions and their neighboring EMI and endometrium, which may result in impaired endometrial repair and subsequent HMB." (PMID 35386380, 2022). "Evidence for reduced HIF‐1α staining, and possibly repressed hypoxia, and PGE2 signaling is shown in our present study in adenomyosis lesions and the neighboring EMI and eutopic endometrial tissues collected during either proliferative or secretory phases." (PMID 35386380, 2022).
allergic contact dermatitis (3 papers, 2017 to 2020). An inflammatory skin condition caused by an immune response to direct contact between the skin and an allergen. "This study aims to investigate the mechanism of calycosin related to tight junctions (TJs) and HIF‐1α both in FITC‐induced mice allergic contact dermatitis and in IL‐1β stimulated HaCaT keratinocytes." (PMID 29993193, 2018). "Moreover, pharmacologic inhibition of HIFs has proven to ameliorate allergic contact dermatitis in human patients.This approach might thus also be a treatment option for IBH, but the exact effects of HIF-1α on effector cells in IBH needs first to be investigated." (PMID 32343720, 2020).
alopecia (3 papers, 2023 to 2024). Hair loss usually from the scalp. "Our findings implicate pharmacological activation of HIF-1α as a promising therapeutic intervention for hair loss in aged individuals and alopecia patients." (PMID 37285263, 2023). "Finally, treatment with a HIF-1α activator enhanced the hair inductive potential of DPCs, indicating that HIF-1α is a promising therapeutic target for treating hair loss." (PMID 36707659, 2023). "Therefore, HIF-1α activators with diverse selectivity and chemical properties have advanced to clinical studies highlighting the translational potential of our findings in repositioning these drugs for alopecia treatment and hair loss prevention." (PMID 37285263, 2023). "Contrary to the alopecia-inducing effects of the earlier hub genes, STAT3, HIF1A, and MAPK3 are reported to counteract hair loss." (PMID 39056691, 2024).
anaplastic astrocytoma (3 papers, 2012 to 2025). "According to the study results, increased HIF-1α expression was observed in 37.5% of diffuse astrocytoma cases, 27.5% of anaplastic astrocytoma cases, and 83.3% of GBM cases." (PMID 40512281, 2025).
Aortic dissection (3 papers, 2019 to 2023). Aortic dissection refers to a tear in the intimal layer of the aorta causing a separation between the intima and the medial layers of the aorta. "Although HIF1A activation likely induces the development of aortic dissection, the relationship between autophagy and hypoxia is poorly understood." (PMID 33066131, 2020).
aortic stenosis (3 papers, 2020 to 2023). Aortic valve stenosis is a aortic valve disease caused by the incomplete opening of the aortic valve. "Studies have identified the expression of HIF-1α, a pro-angiogenic transcription factor, in the calcific leaflet nodule of aortic stenosis (AS)." (PMID 37446282, 2023). "The accentuation seen over time of these myocardial structural changes may have been responsible for increasing HIF-1α in the different phases of aortic stenosis." (PMID 37047174, 2023).
bacterial meningitis (3 papers, 2020 to 2022). Inflammation of the membranes surrounding the brain and spinal cord due to a bacterial infection. "Immunohistochemistry of murine pneumococcal meningitis samples revealed activated HIF-1α in the brain and this finding was confirmed in human pneumococcal and other bacterial meningitis autopsy specimen." (PMID 32529267, 2020).
benign ovarian tumors (3 papers, 2013 to 2022). "It was found that the positive expression rates of Glut1, HIF-1α, and Ki67 in CD4+ Treg cells of OC were significantly higher than that in benign ovarian tumor and HC, and also significantly higher than that in CD4+ Teffs of OC." (PMID 33414414, 2021). "The normal ovary tissues, benign ovarian tumors, and borderline ovarian tumors were studied to reveal that TLR4, NF-κBp65, and HIF-1α were expressed at a low level, while as cancer progressed, the proportion of the TLR4+ve, NF-κBp65+ve, and HIF-1α+ve EOC cells were significantly increased." (PMID 35464826, 2022).
bladder urothelial carcinoma (3 papers, 2016 to 2020). "Hypoxia-inducible factor-1 alpha (HIF-1α) protein expression is an unfavorable prognostic factor in bladder urothelial carcinoma as it can up-regulate FGFR3, VEGF, and GLUT-1 which contribute to tumor cell survival, tumor angiogenesis, and aerobic glycolysis in response to tumor hypoxia." (PMID 27557492, 2016).
carcinoma in situ (3 papers, 2015 to 2023). "In agreement with previous reports, CAIX expression was positively correlated with tumour size, grade, and HER2 positivity, whilst the presence of in situ carcinoma associated with HIF-1α positivity." (PMID 37166494, 2023).
cerebral edema (3 papers, 2020 to 2025). "Prior research has indicated that AQP4 and HIF-1α may have a synergistic effect in the pathogenesis of cerebral edema." (PMID 39619615, 2024).
cholestasis (3 papers, 2017 to 2023). Impairment of the bile flow caused by obstruction within the liver, or outside the liver in the bile duct system. "A mechanism whereby cholesterol loading of hepatocytes activates HIF-1α and induces chronic hypoxic responses was revealed in vitro, in isolated hepatocytes; in vivo, using an atherogenic diet; and in a bile duct ligation model of cholestasis." (PMID 29955245, 2018).
chronic pancreatitis (3 papers, 2021 to 2025). A chronic inflammatory process causing damage and fibrosis of the pancreatic parenchyma. "In summary, our studies reveal a neddylation/HIF-1α/CCL5 axis in regulating macrophage infiltration in chronic pancreatitis and further represent new ideas for therapeutic strategy and disease treatment." (PMID 33723230, 2021). "Thus, HIF-1α acts as a potent modulator of neddylation-induced CCL5 expression in chronic pancreatitis." (PMID 33723230, 2021).
co-infection (3 papers, 2019 to 2024). "We propose that the elevated levels of VEGF-A observed during HIV/SARS-CoV-2 co-infection originate predominantly from activated immune cells due to the upregulation of HIF-1α by damaged endothelial cells." (PMID 40008234, 2024). "Co-infection of AAV5-shHIF-1α reversed the effect of AMO-19 and inhibited the level of CD31 and HIF-1α." (PMID 33352533, 2020). "In the case of SARS-CoV-2/HIV co-infection, we speculate that the elevated levels of VEGF-A observed in this clinical setting originate predominantly from activated immune cells because of upregulation of HIF-1α by damaged endothelial cells." (PMID 40008234, 2024).
cutaneous leishmaniasis (3 papers, 2018 to 2024). Leishmaniasis affecting the skin. "During cutaneous leishmaniasis, lesions from human patients contain elevated levels of HIF-1α and the HIF target Vegfa." (PMID 38190401, 2024). "In cutaneous leishmaniasis, both HIF1α and HIF2α are active but it is suggested that hypoxia promotes macrophage phagocytosis in a HIF1α-dependent manner, while HIF2α acts as a phagocytic repressor during Leishmania infection." (PMID 39543383, 2024). "Therefore, it is very likely that the differential context of HIF-1α stabilization in visceral and cutaneous leishmaniasis impacts on the functional consequence of HIF-1α activation." (PMID 29520262, 2018).
cutaneous squamous cell carcinoma (3 papers, 2018 to 2021). "Findings demonstrating HIF-1α regulation by microRNA in UM have been reported by Xia and colleagues, who evidenced promotion of HIF-1α signaling and migration of UM cell by miR-652 through the repression of HOXA9, a negative regulator of HIF-1 expression in cutaneous squamous cell carcinoma." (PMID 33964953, 2021).
delirium (3 papers, 2024 to 2025). A disorder characterized by confusion; inattentiveness; disorientation; illusions; hallucinations; agitation; and in some instances autonomic nervous system overactivity. "Based on these findings, we hypothesize that HIF-1α plays a pivotal role in the pathophysiology of postoperative delirium in elderly patients and that Dex may exert its preventive effects through modulation of the HIF-1α signaling pathway." (PMID 41431031, 2025). "This review explores the hypothesis that dexmedetomidine may prevent POD in elderly patients by modulating HIF-1α pathways to provide novel insights into potential therapeutic targets for the prevention and treatment of Dex-induced postoperative delirium in geriatric patients." (PMID 41431031, 2025).
dilated cardiomyopathy (3 papers, 2022 to 2025). Cardiomyopathy which is characterized by dilation and contractile dysfunction of the left and right ventricles. "For example, chronic HIF1α activation in the heart, such as through the cardiac-specific inactivation of EglN family members or cardiac-specific expression of a stabilized version of HIF1α, causes a dilated cardiomyopathy." (PMID 36106637, 2022). "However, sustained activation of HIF-1α in the heart eventually results in dilated cardiomyopathy with a variety of histological changes, including myocyte loss and fibrosis." (PMID 36089604, 2022).
E. coli infection (3 papers, 2020 to 2023). "Firstly, we observed a significant decrease in HIF-1α expression after inhibiting CSE during E. coli infection." (PMID 37644526, 2023).
edema (3 papers, 2020 to 2023). An abnormal accumulation of fluid beneath the skin, or in one or more cavities of the body. "Thus, inhibition of PI3K/AKT/mTOR/HIF-1α/VEGF signaling pathway could reduce the injuries of ALI such as exaggerated inflammatory response and pulmonary edema." (PMID 34183011, 2021).
Encephalopathy (3 papers, 2014 to 2025). Encephalopathy is a term that means brain disease, damage, or malfunction. "Decreased α KG also leads to increased HIF1 α, which induces VEGF, already increased at baseline and exacerbated further during encephalopathy." (PMID 24468193, 2014).
endometrioid tumor (3 papers, 2014 to 2016). A benign, borderline, or malignant epithelial tumor of the female reproductive system characterized by the presence of glands and/or cysts lined by neoplastic cells that resemble endometrial cells. "To determine the relationships among DEC1, HIF-1α and c-Myc expression in tumor specimens, we analyzed a microarray gene expression profiling dataset derived from 285 serous and endometrioid tumors of ovary, peritoneum, and fallopian tube using affynetrix U133 Plus 2 arrays (NCBI GSE9891)." (PMID 27765932, 2016). "Compared to endometrioid tumors, the expression of anti-HIF-1α antibody was significantly higher in nonendometrioid malignancies (P = 0.0115)." (PMID 24745019, 2014).
endometritis (3 papers, 2024 to 2026). An acute or chronic, usually bacterial infectious process affecting the endometrium. "In conclusion, CA inhibits inflammation and ferroptosis by regulating AMPKα/mTOR/HIF‐1α signalling pathway to alleviate S. aureus‐induced endometritis in mice." (PMID 39462269, 2024). "A well-known functional connection between inflammation, such as endometritis, and hypoxia exists, which is largely regulated by HIF-1α." (PMID 39337320, 2024). "Interestingly, the level of HIF-1A mRNA was strongly increased after LPS treatment and furthermore HIF-1α/ARNT consensus binding motifs were highly enriched in the hypo-methylated DMRs supporting a functional role for these transcription factors in this endometritis model." (PMID 39337320, 2024).
epithelial dysplasia (3 papers, 2011 to 2025). "The IHC method was carried out to observe whether there were differences in the expressions of UBE2S, HIF‐1α, and FOXM1 in low‐grade intraepithelial neoplasia (LIN), high‐grade intraepithelial neoplasia (HIN), and the normal epithelial tissues of the esophagus." (PMID 41427004, 2025).
epithelial ovarian tumors (3 papers, 2012 to 2024). "A previous study revealed that ADM upregulates HIF-1α and VEGF to promote angiogenesis in epithelial ovarian tumors." (PMID 38311733, 2024).